BEX2 (brain expressed X-linked 2)
Diseases named in the same sentence as BEX2 in open-access papers (continued):
Sharing a sentence is not in itself a finding about the gene and the disease.
cancer (17 papers, 2010 to 2025). A tumor composed of atypical neoplastic, often pleomorphic cells that invade other tissues. "High BEX2 expression has been previously implicated in the maintenance of cancer stem cells and poor prognosis in HCC." (PMID 39005337, 2024). "Resistance to chemotherapeutic agents, such as cisplatin and gemcitabine in patients was associated with the upregulation of BEX2 in different cancer types, like HCC and pancreatic adenocarcinoma." (PMID 37777549, 2023). "The BEX2 (brain expressed X-linked gene 2) gene is mapped on the mouse X chromosome and human Xq227, and encodes an approximately 20-kDa protein detected in some types of cancer." (PMID 33299012, 2020). "Genes such as APRT, CCL2, BEX2, MGC26963, and PLAU were identified as key genes significantly associated with cancer progression." (PMID 38970097, 2024). "Together, these results demonstrate that BEX2 inhibits doxorubicin-induced cancer cell death in vivo." (PMID 37777549, 2023). "BEX2 down-regulation induced G1 cell cycle arrest and sensitized cancer cells to pro-apoptotic agents." (PMID 38107402, 2023). "The BSCE omic-scale data were rich in examples for Bex2 down-regulation in a wide variety of infectious diseases and cancers." (PMID 38107402, 2023). "Clinically, the level of BEX2 is upregulated in LUAD and is associated with poor prognosis in lymph node metastasis-free cancer." (PMID 37777549, 2023). "Further, it was shown that BEX2 functions like an oncogene, activates the NF-kB pathway, and promotes the propagation of human cancer cells." (PMID 35646666, 2022). "Earlier studies have shown that BEX2 is the target gene of p65/RelA in cancers and, as a feedback mechanism, regulates the phosphorylation/activity of p65/RelA." (PMID 35646666, 2022). "Collectively, we conclude that BEX2 is potentially required for the maintenance of dormant cancer stem cells." (PMID 33299012, 2020). "To investigate molecular mechanisms of the BEX2-mediated maintenance of dormant cancer stem cells, we screened for BEX2-binding proteins and identified TUFM, which is a translation elongation factor of tRNA19." (PMID 33299012, 2020). "Taken together, these data indicate that BEX2 is involved in the regulation of tumorigenesis and metastasis, and its potential functions largely depend on the cancer type and cell-specific context." (PMID 31929751, 2020). "Although these data suggest that BEX2 is involved in the function of normal stem cells as well as cancer stem cells, our findings shed light on how controlling BEX2 can result in attenuation of CSC phenotypes and therapy resistance." (PMID 33299012, 2020). "Given that one of the hallmarks of cancer stem cells is their dormant phase, we examined the cell cycle in BEX2-knockdown cell lines." (PMID 33299012, 2020). "The available data in different cancers suggest that BEX2 expression can be regulated by a variety of mechanisms." (PMID 20482821, 2010). "Specifically, we observed downregulation of the BEX2 Signaling Pathway, which is critical for modulating apoptosis in various cancer cell types, suggesting that in our experiments, the SHV pulses might have caused apoptosis via plasma membrane damage." (PMID 39967849, 2025). "How BEX2 regulates chemoresistance in cancer cells is yet to be identified." (PMID 37777549, 2023). "The flow cytometry analysis also showed that overexpression of BEX2K59R increased the levels of apoptosis compared with the group of BEX2 overexpression, suggesting that BEX2 crotonylation modification plays a critical role in inhibiting apoptosis in NSCLC cancer cells." (PMID 37777549, 2023). "Bex2 has been described as an oncogene and a dormant cancer stem cell-related protein." (PMID 38107402, 2023). "Here, we investigated how BEX2 regulated cancer cell apoptosis in a mitophagy-dependent manner." (PMID 37777549, 2023). "Interestingly, a recent study has reported that BEX2 is crucial for maintaining dormant cancer stem cells through the suppression of mitochondrial activity." (PMID 35646666, 2022).
cancer (continued). "Thus, the precise function of BEX2 is controversial and little is known about what molecule(s) interact with BEX2 in cancer." (PMID 33299012, 2020). "To examine whether BEX2 is involved in cancer stem cell properties, we established two HuCCT1 BEX2-knockdown cell sublines, which expressed minimal BEX2 as indicated by real-time PCR and western blotting analysis." (PMID 33299012, 2020). "BEX2 expression could possibly be modulated by the aberrantly activated mechanistic target of rapamycin (mTOR) in cancer cells." (PMID 27297407, 2016). "We hypothesized that BEX2 might promote mitophagy to resist cell apoptosis in cancer cells." (PMID 37777549, 2023). "Consistently with BEX2, ARIH1-induced mitophagy has been found to enhance the resistance of cancer cells to chemotherapy-induced cell death." (PMID 37777549, 2023). "Expression of BEX1, BEX2, BEX4, and BEX5 were found to be reduced in different human cancers." (PMID 28083995, 2017).
infection (2 papers, 2010 to 2023). The state of being infected such as from the introduction of a foreign agent such as serum, vaccine, antigenic substance or organism. "On the other hand, the highest ranked down-regulated gene (in pattern IV) across all dpi was Bex2 (brain-expressed X-linked 2), while Bex1 and Bex4 trended similarly downward over the course of infection." (PMID 38107402, 2023). "Down-regulation of Bex2 occurs earlier in infection for young and aged mice treated with the most severe SARS-CoV-1 variant (MA15) compared to the weakest variant (MA15e)." (PMID 38107402, 2023). "Interestingly, our microarray data showed that the expression level of BEX2, GLRX3, GPX1 and PXCARD were down-regulated at 4 days post-infection, which is different from the up-regulated mRNA level at 8 hours post infection." (PMID 21172007, 2010).
neurological disorders (1 paper, 2021). "BEX2 expression was favorably found in embryonic brain, which has a vital role in the nervous system development and related neurological disorders." (PMID 34803456, 2021). "Bex2 is well known for its role in the nervous system, and is associated with neurological disorders, but its role in the lung’s physiology is still not reported." (PMID 34803456, 2021).
BEX2 also shares sentences with these, for which no sentence is quoted: malignant glioma (3 papers); brain tumors (2); colon cancer (2); Allergy (1); astroglioma (1); atherosclerosis (1); gastric cancer (1); head and neck squamous cell carcinoma (1); immune deficiency (1); infectious disease (1); melanoma (1); metabolic disease (1); Obesity (1); pulmonary fibrosis (1); skin carcinoma (1).